H19 (H19 imprinted maternally expressed transcript)
Diseases named in the same sentence as H19 in open-access papers (continued):
Sharing a sentence is not in itself a finding about the gene and the disease.
Cerebral ischemia (11 papers, 2017 to 2025). Restriction of arterial blood supply to the brain associated with insufficient oxygenation to support the metabolic requirements of the tissue. "Hypoxia is a major cause of cerebral ischemia and reperfusion (I/R) injury, which can stimulate the expression of lncRNA H19 through activating hypoxia induced factor 1α." (PMID 28203482, 2017). "It has been shown that patients after cerebral ischemia have increased levels of lncRNA H19 in the blood, which promotes the development of neuroinflammation by driving histone deacetylase 1-dependent M1 microglial polarization." (PMID 41245147, 2025). "In patients after brain ischemia, synchronized overexpression of lncRNA H19 and tumor necrosis factor C1q-related protein 6 (C1QTNF6) and decreased expression of miRNA-29b were found in leukocytes." (PMID 41245147, 2025). "Similar changes in the expression of lncRNA H19 and miRNA-29b were found after the first day of recirculation following local brain ischemia in rats." (PMID 41245147, 2025). "This study aimed to explore the effects of long noncoding RNA (lncRNA) H19 knockdown on angiogenesis and blood–brain barrier (BBB) integrity following cerebral ischemia/reperfusion (I/R) and elucidate their underlying regulatory mechanisms." (PMID 39161158, 2024). "Our findings demonstrate the inflammation‐modulatory effect of the H19/miR‐29b/C1QTNF6 axis in the mechanism of cerebral ischemia injury." (PMID 35322553, 2022). "For example, LncRNA H19 induces autophagic cell death in cerebral ischemia and reperfusion (I/R) injury by inhibiting DUSP5 to phosphorylate ERK1/2 and provoke autophagy." (PMID 34759263, 2021). "We previously revealed that H19 expression functions in cerebral ischemia through activating neuronal autophagy and promoting microglial M1 phenotype polarization." (PMID 33101034, 2020). "For instance, in a rat brain with cerebral ischemia and reperfusion injury, H19 has been shown to activate the autophagy process through the DUSP5-ERK1/2 axis." (PMID 31340867, 2019). "Moreover, after reversible experimental local cerebral ischemia, lncRNA H19 was shown to promote leukocyte activation via the miRNA-29b/C1QTNF6 axis, triggering the release of TNF-α and IL-1β, which enhanced neuroinflammation." (PMID 41245147, 2025). "Mice in the I/R + sh‐H19 group showed enhanced neurological functional recovery following cerebral ischemia relative to those in the I/R + sh‐NC group, as indicated by reduced foot slips (both hind and front legs) during the beam balance test on day 7 after cerebral ischemic injury (p < 0.001)." (PMID 39161158, 2024). "However, the effects of H19 silencing on cerebral blood flow following cerebral ischemia remain to be elucidated." (PMID 39161158, 2024). "The perinatal nicotine exposure-mediated H19 repression may contribute to the miR-181a overexpression and the development of brain ischemia-sensitive phenotype in postnatal offspring." (PMID 35805891, 2022). "LncRNA H19 can inhibit autophagy in a cell model of cerebral ischemia–reperfusion (OGD/R)." (PMID 33881140, 2021). "Furthermore, the protective effect of H19 siRNA was abrogated by autophagy activator, RAP, suggesting that lncRNA H19 induced cerebral ischemia and reperfusion injury by activating autophagy process." (PMID 28203482, 2017). "However, the impact of lncRNA H19 on angiogenesis and the BBB following cerebral ischemia and its underlying regulatory pathways remains unknown despite extensive investigations over the years." (PMID 39161158, 2024). "LncRNA H19 acts as a ceRNA of mir-19a-3p to target PTEN and promote cerebral ischemia/reperfusion injury via PI3K/AKT pathway." (PMID 35601501, 2022). "Long non-coding RNA H19 (lncRNA H19) was found to be upregulated by hypoxia, its expression and function have never been tested in cerebral ischemia and reperfusion (I/R) injury." (PMID 28203482, 2017).
Cirrhosis (11 papers, 2016 to 2024). A chronic disorder of the liver in which liver tissue becomes scarred and is partially replaced by regenerative nodules and fibrotic tissue resulting in loss of liver function. "In liver, H19 regulates the trans-differentiation of hepatic stellate cells into myofibroblasts, which is an important step in the pathogenesis of cirrhosis, and the inhibition of H19 has been recommended for anti-fibrosis therapy." (PMID 33923324, 2021). "Recent studies have demonstrated H19 increased in the liver of patients with fibrosis and cirrhosis, regardless of the underlying disease." (PMID 37398637, 2023). "In contrast to HOTTIP, H19 and MEG3, we found that ANRIL expression was up-regulated both in cirrhosis vs. normal liver and in HCC vs. cirrhosis, suggesting its involvement in the process of hepatocarcinogenesis from normal liver through the precancerous stage of cirrhosis." (PMID 27894309, 2016).
fibrosis (11 papers, 2016 to 2025). the formation of excess fibrous connective tissue in an organ or tissue in a reparative or reactive process. "The aim of the current study is to investigate the roles of long non-coding RNA H19 (lncRNA H19) in the pulmonary inflammation and fibrosis of IPF." (PMID 33138822, 2020). "In another study, lncRNA H19 was significantly upregulated in the infarct area in mouse model and acted to antagonize Y-box-binding protein (YB)-1 through direct interaction, resulting in cardiac fibrosis." (PMID 33390954, 2020). "In this study, we unraveled the crucial role of an interaction between H19-YB-1 in regulating cardiac fibrosis after infarction and demonstrated that lncRNA H19 is an ECM regulator which may serve as a therapeutic target for ischemic cardiomyopathy." (PMID 31588235, 2019).
Hepatic steatosis (11 papers, 2020 to 2025). Steatosis is a term used to denote lipid accumulation within hepatocytes. "In summary, we demonstrated that lncRNA H19 expression was associated with hepatic steatosis and the development of HFD‐induced NAFLD in mice." (PMID 31809000, 2020). "Long non-coding RNA H19 (lncRNA H19) plays an important role in lipid metabolism, however, its relationship with metabolic dysfunction-associated fatty liver disease (MAFLD) remains unclear." (PMID 40101079, 2025). "Studies showed that the overexpression of H19 results in hepatic metabolic reprogramming and worsens diet-induced fatty liver." (PMID 41226441, 2025). "Mechanistically, H19 induces hepatic steatosis by activating the MLXIPL and mTORC1 networks in hepatocytes." (PMID 35016686, 2022). "H19 increased hepatic steatosis by upregulating mTORC1 and MLXIPL in hepatocytes, according to hepatocyte implantation experiments." (PMID 36552725, 2022). "In another study of high-fat diet mice, H19 lncRNA acts as a sponge to miR-130a to upregulate peroxisome proliferator-activated receptor gamma (Pparg) expression, concomitant with hepatic steatosis." (PMID 35052690, 2021). "One such is the lncRNA H19 imprinted maternally expressed transcript (H19), which is one of the essential lncRNAs in hepatic steatosis." (PMID 35052690, 2021). "Hepatocyte implantation studies further confirmed that H19 promoted hepatic steatosis by up‐regulating both mTORC1 and MLXIPL in hepatocytes." (PMID 31809000, 2020). "We further analysed the essential role of Mlxipl in H19‐promoted hepatic steatosis by silencing endogenous Mlxipl expression." (PMID 31809000, 2020). "In vivo hepatocyte implantation studies further confirm that H19 promoted hepatic steatosis by up‐regulating both mTORC1 signalling axis and MLXIPL transcriptional network." (PMID 31809000, 2020). "Mechanistically, we found that H19 promoted hepatic steatosis by up‐regulating and the mTORC1 signalling axis (including active RAPTOR, mTOR, S6K SREBP and suppress LIPIN1) and MLXIPL transcriptional network in hepatocytes." (PMID 31809000, 2020). "Mechanistically, H19 was shown to promote hepatic steatosis by up‐regulating lipogenic transcription factor MLXIPL." (PMID 31809000, 2020). "Despite the recognized significance of lncRNA H19 in diet-induced hepatic steatosis and glucose metabolism, it remains unclear whether and how lncRNA H19 is involved in MAFLD disease progression." (PMID 40101079, 2025). "By upregulating MLXIPL/ChREBP and silencing, Mlxipl reduced H19-induced hepatic steatosis." (PMID 36552725, 2022). "Also, prolonged-expression of H19 facilitates lipid accumulation in hepatocytes, enhances hepatic steatosis development, and metabolic pathway disruption." (PMID 33622377, 2021). "The role H19 in cellular senescence of hepatic endothelium is unknown, although H19 induces hepatic steatosis." (PMID 34220553, 2021). "Taken together, these results suggest that MLXIPL may be an important mediator of H19‐promoted hepatic steatosis." (PMID 31809000, 2020). "Considering the important role of mTORC1 in lipid metabolism, we also analysed whether the mTORC1 signalling was involved in H19‐induced hepatic steatosis." (PMID 31809000, 2020). "Control IgG of masses was shown.Collectively, these results strongly suggest that lncRNA H19 may promote hepatic steatosis by up‐regulating both mTORC1 signalling complex and MLXIPL transcriptional network in hepatocytes." (PMID 31809000, 2020). "Therefore, the interaction between H19 and miR-130a to regulate Srebf1 could be the primary driver for hepatic steatosis." (PMID 35052690, 2021). "Mechanistically, we showed that H19 promoted hepatic steatosis by up‐regulating MLXIPL/ChREBP and silencing Mlxipl diminished H19‐induced lipid accumulation in hepatocytes." (PMID 31809000, 2020).
Hepatic steatosis (continued). "It has also been demonstrated that expression of H19 activates the mammalian target of rapamycin complex 1 signaling and the lipogenic transcription factor MLX interacting protein-like pathways, which are involved in hepatic steatosis production." (PMID 41226441, 2025). "In addition to H19, several other lncRNAs are involved in NAFLD pathogenesis, particularly in liver steatosis." (PMID 35016686, 2022).
Hypertension (11 papers, 2016 to 2025). The presence of chronic increased pressure in the systemic arterial system. "SNPs of the H19 gene were found to modify its expression and are related to risk factors for cardiovascular and cerebrovascular diseases, e.g., obesity and hypertension." (PMID 38255915, 2024). "Nevertheless, the genotype distribution of H19 rs217727 polymorphisms among cases of diabetic hypertensive CIS matches the Hardy–Weinberg equilibrium at p =0.094." (PMID 38255915, 2024). "Moreover, polymorphisms of the H19 gene have been reported to alter levels of H19, which are associated with risk factors for cardiovascular diseases, such as high blood pressure." (PMID 34445422, 2021). "Placental tissues from preeclampsia patients diagnosed with hypertension exhibit significantly higher H19 levels." (PMID 33154191, 2020). "H19 might aggravate hypertension by inducing excessive autophagy and cell death." (PMID 33154191, 2020).
papillary thyroid carcinoma (11 papers, 2018 to 2024). "Studies have shown both oncogenic and tumor suppressor function of H19 in papillary thyroid carcinoma." (PMID 39659621, 2024). "Similar data have been shown in papillary thyroid carcinoma cells in which estradiol (E2) significantly promotes H19 transcription via ERβ and elevates H19 expression." (PMID 33291403, 2020). "Depletion of H19 reverses E2-induced stem-like properties, indicating the importance of the positive feedback loop in the enrichment of papillary thyroid carcinoma stem cells." (PMID 33291403, 2020). "In papillary thyroid carcinoma cells, H19 serves as a molecular sponge for miRNA-3126-5p to mutually induce ERβ expression." (PMID 32759784, 2020). "The estradiol-induced expression of H19 is also involved in the pathogenesis of papillary thyroid carcinoma." (PMID 32759784, 2020). "Previous studies have reported that H19 was downregulated in papillary thyroid carcinoma compared with adjacent paracancerous tissues." (PMID 30536700, 2019). "Decreased lncRNA H19 expression resulted in cell proliferation and migration in papillary thyroid carcinoma cell line and may contribute to lymph node metastasis." (PMID 34526543, 2021). "We have recently found that expression of H19 was lower in the papillary thyroid carcinoma (PTC) tissues, and low expression of H19 was associated with extrathyroid extension, pathological lateral node metastasis, histological aggressive type and poorer disease-free survival." (PMID 31791180, 2019). "And the oncogenic role of H19 was revealed in patients with papillary thyroid carcinoma." (PMID 31649871, 2019). "Papillary thyroid cancer samples showed a heterogeneous expression of H19." (PMID 29561759, 2018). "Similarly, H19 is overexpressed in papillary thyroid carcinoma cells through estradiol (E2); H19 overexpression is associated with increased stemness-related factors expression, increased ADLH+ population, and sphere forming capacity as well as enhanced tumor growth." (PMID 33291403, 2020).
acute myeloid leukemia (10 papers, 2013 to 2024). Acute myeloid leukemia (AML) is a group of neoplasms arising from precursor cells committed to the myeloid cell-line differentiation. "As a precursor of miR-675, imprinting of the lncRNA H19 controls mouse hematopoietic stem cell quiescence and is highly associated with chronic myeloid leukemia, chronic myelomonocytic leukemia, and acute myelogenous leukemia." (PMID 28624809, 2017). "H19 expression is markedly elevated in acute myeloid leukemia (AML)." (PMID 38355574, 2024). "Furthermore, lncRNA H19 sponged and downregulated miR-29a-3p in both acute myeloid leukemia (AML) and osteosarcoma, which prevented cell death and enhanced cell proliferation, migration, and invasion." (PMID 36355327, 2023). "Moreover, MEG3, UCA1, and H19 are upregulated in acute myeloid leukemia." (PMID 26448935, 2015). "We found that two lncRNAs including MEG3 and H19 are up-regulated in acute myeloid leukemia (AML) cancer compared to normal blood cells (Fold change > 1.5, P-value < 0.01)." (PMID 24312125, 2013). "However, the potential role of H19 and its clinical significance in acute myeloid leukemia (AML) remain largely elusive." (PMID 29643943, 2018). "We found that lncRNA H19 had a high score of 0.84 for acute myeloid leukaemia, which was ranked in the top 8% and not included in the latest version of LncRNADisease." (PMID 31787106, 2019).
rheumatoid arthritis (10 papers, 2013 to 2025). A chronic, systemic autoimmune disorder characterized by inflammation in the synovial membranes and articular surfaces. "AFF3 is an immunoglobulin class switch factor that has been shown to be a susceptibility factor for rheumatoid arthritis, and H19 has been shown to regulate ISG expression in macrophages in response to lipopolysaccharide stimulation." (PMID 39415484, 2025). "Pathway analysis of the DEGs did not identify any IFN‐related pathways, but AFF3 and H19, which are two of the most significant DEGs, have tentatively been implicated in immune responses in other autoimmune conditions including rheumatoid arthritis." (PMID 39415484, 2025). "The lncRNAs HOTAIR, lincRNA‐p21, lncRNA H19 and MALAT1 play important roles in the clinical diagnosis and progression of rheumatoid arthritis (RA)." (PMID 36607351, 2023). "But for patients with rheumatoid arthritis complicated with IPF, targeting H19 seems beneficial for disease progression." (PMID 36685535, 2022). "Additionally, compared to rheumatoid arthritis (RA) and irritable bowel syndrome (IBS) patients, H19 expression in plasma EVs was significantly elevated, confirming that H19 can serve as a potential biomarker for IBD with strong discriminatory ability." (PMID 40243658, 2025).
ulcerative colitis (10 papers, 2017 to 2026). An inflammatory bowel disease involving the mucosal surface of the large intestine and rectum. "The H19-miR675-5p-VDR pathway increases VDR expression level in AS, but in ulcerative colitis, H19 overexpression decreased VDR expression through the same pathway." (PMID 38475720, 2024). "Since it has been verified that the overexpression of ICAM-1 and CXCR4 can promote the homing of MSC in the treatment of ulcerative colitis, the overexpression of H19 exhibited therapeutic effects in ulcerative colitis." (PMID 34630738, 2021). "H19 expression increases in patients with ulcerative colitis." (PMID 33767583, 2021). "H19 and IFNG-AS1 might be associated with ulcerative colitis." (PMID 35571069, 2022). "In summary, the overexpression of H19 in MSC downregulated miR-139 and miR-141, thus increasing the activity of their targets ICAM-1 and CXCR4, respectively, to exhibit therapeutic effects in ulcerative colitis." (PMID 34630738, 2021). "In this study, we treated ulcerative colitis animals with MSC preconditioned with or without H19 and compared the therapeutic effect of MSC and MSC-H19 in the treatment of ulcerative colitis." (PMID 34630738, 2021). "In this study, we treated ulcerative colitis animals with MSC preconditioned with or without H19 and compared the therapeutic effect of MSC and MSC-H19." (PMID 34630738, 2021).